AKAP12 (A-kinase anchoring protein 12)
Diseases named in the same sentence as AKAP12 in open-access papers (continued):
Sharing a sentence is not in itself a finding about the gene and the disease.
Stroke (3 papers, 2013 to 2024). Sudden impairment of blood flow to a part of the brain due to occlusion or rupture of an artery to the brain. "BBB damage/dysfunction is one of the major hallmarks of stroke, which causes edema formation, and in a rat stroke model, it is implied that AKAP12 expression was negatively correlated with edema formation after stroke." (PMID 33260683, 2020). "Lastly, although our current study demonstrates that AKAP12 is an important endogenous molecule for suppressing deleterious cascades causing BBB damage after stroke, we need to consider how to translate this finding into clinical practice." (PMID 33260683, 2020). "Thus, AKAP12 may serve as a novel therapeutic target for cognitive decline associated with stroke or other CNS diseases." (PMID 39574214, 2024). "Our experiment with a Rho kinase inhibitor Y-27632 provides a proof-of-concept that the AKAP12-Rho pathway can be a therapeutic target for stroke." (PMID 33260683, 2020). "In a mouse model of focal ischemia, the expression level of AKAP12 in cerebral endothelial cells was upregulated during the acute phase of stroke." (PMID 33260683, 2020). "Although our findings demonstrate the importance of AKAP12 in BBB tightness after stroke, there are some caveats and limitations that need to be addressed in future studies." (PMID 33260683, 2020). "Our current study supports and even expands these findings by showing the BBB-supportive roles of AKAP12 during the acute phase of stroke." (PMID 33260683, 2020). "Therefore, in this study we used in vitro and in vivo systems to examine the roles of AKAP12 in BBB function during the acute phase of stroke." (PMID 33260683, 2020). "Furthermore, in vitro experiments using cultured cerebral endothelial cells (HBMECs) confirmed that AKAP12 expression was upregulated after in-vitro stroke conditions (e.g., oxygen-glucose deprivation: OGD)." (PMID 33260683, 2020). "We first examined expression patterns of AKAP12 after stroke in mice." (PMID 33260683, 2020). "We then investigated whether AKAP12 has a supportive or detrimental role for BBB tightness after stroke by comparing Akap12 knockout mice to wild type mice." (PMID 33260683, 2020). "Therefore, roles of endothelial-AKAP12 during the chronic phase of stroke should be carefully examined in the future to further our understandings of the roles of AKAP12 in stroke pathology." (PMID 33260683, 2020). "In addition, in a mouse stroke model, AKAP12-positive cells in fibrotic scars restrict immune cells from entering the site of injury, which enhances CNS recovery." (PMID 33260683, 2020). "Therefore, future studies are warranted to investigate the roles of astrocyte- and/or pericyte-AKAP12 in BBB function after stroke." (PMID 33260683, 2020). "During the acute phase of stroke, AKAP12 expression transiently increased in the affected region." (PMID 33260683, 2020). "Therefore, the AKAP12-rho-kinase signaling pathway represents a novel therapeutic target for stroke." (PMID 33260683, 2020). "Therefore, investigations into the downstream pathways of AKAP12 will provide a hint to determine novel therapeutic targets to develop effective drugs for stroke." (PMID 33260683, 2020). "Compared to wild-type mice, Akap12 knockout mice showed a larger extent of BBB damage after stroke." (PMID 33260683, 2020). "Also in vivo, compared to wild type mice, Akap12 knockout mice showed a larger level of MLC phosphorylation in the ipsilateral side after stroke." (PMID 33260683, 2020). "Finally, cognitive decline/dysfunction may result from brain pathology, such as stroke and vascular dementia, and therefore, future research should investigate the role of AKAP12 in the pathological mechanisms of brain disease." (PMID 39574214, 2024).
Stroke (continued). "Because BBB damage and dysfunction are a major hallmark in stroke pathology, and because BBB tightness may be disrupted by reperfusion injury after re-canalization in stroke patients, AKAP12 signaling can be a novel and effective therapeutic target for acute stroke injury." (PMID 33260683, 2020). "Interestingly, Y-27632 treatment suppressed the cell death/damage in endothelial cells in Akap12 knockout mice, supporting the idea that the AKAP12-Rho pathway may be an effective therapeutic target for stroke." (PMID 33260683, 2020). "Therefore, our findings that AKAP12 signaling is involved in the regulation of BBB tightness under stroke conditions provide a hint towards the development of a novel therapy to protect BBB function for stroke patients." (PMID 33260683, 2020). "In addition, the treatment of Rho kinase inhibitor Y-27632 suppressed IgG leakage in Akap12 knockout stroke mice, which was consistent with our in vitro findings that the activation of Rho signaling pathway causes endothelial leakiness under the conditions of AKAP12 downregulation." (PMID 33260683, 2020). "The FACS analysis showed that Akap12 knockout mice exhibited larger numbers of ssDNA-positive CD31 cells (i.e., damaged/dead endothelial cells) after stroke." (PMID 33260683, 2020). "AKAP12 is known to regulate the secretion of multiple growth factors, including VEGF, which shows biphasic roles after stroke." (PMID 33260683, 2020). "In summary, our current study demonstrates that endogenous AKAP12 works to alleviate the damage and dysfunction of the BBB during the acute phase of stroke." (PMID 33260683, 2020). "Western blotting with endothelial fractions (e.g., isolated brain microvessels) from non-ischemic or ischemic regions showed that endothelial-AKAP12 expression indeed increased after stroke." (PMID 33260683, 2020). "Gaining an understanding of the balance between AKAP12 and HIF-1 may reveal unknown mechanisms of stroke pathology." (PMID 33260683, 2020). "Second, we did not examine the roles of endothelial-AKAP12 during the chronic phase of stroke." (PMID 33260683, 2020).
benign meningioma (2 papers, 2018 to 2020). A grade I, slowly growing meningioma. "AKAP12 knockdown in benign meningioma cells SF4433 increases proliferation, cell cycle, migration, invasion, and confers an anaplastic profile." (PMID 29391485, 2018).
bladder cancer (2 papers, 2022 to 2023). "Studies have discovered that AKAP12 acts as an oncogenesis suppressor, for example, AKAP12 deficiency is linked to enhanced metastatic potential in human tumors such as bladder cancer." (PMID 35677536, 2022). "Here, the GSEA results also showed that G2M checkpoint pathway was significantly enriched in AKAP12 low expression group, indicating cell cycle regulation role of AKAP12 in progression of bladder cancer." (PMID 37795791, 2023). "Results showed that AKAP12 might be involved in cell cycle and immune regulation in bladder cancer progression for the observed enrichment of G2M checkpoint and interferon α/γ response pathway in low AKAP12 expression group." (PMID 37795791, 2023). "Moreover, we evaluated the prognosis of AKAP12 in bladder cancer." (PMID 37795791, 2023).
breast tumors (2 papers, 2018 to 2025). "In contrast, AKAP12 exhibited hypermethylation and was downregulated in breast tumors, with cfDNA analysis confirming hypermethylation within intron 2 (329 bp) in NAF BrC samples." (PMID 40943642, 2025).
chronic kidney disease (2 papers, 2013 to 2018). Impairment of the renal function secondary to chronic kidney damage persisting for three or more months. "The intronic rs756009 A to G polymorphism in gravin (AKAP12) was associated with a higher risk of chronic kidney disease in Japanese patients with condition that also involves hypertension, diabetes, and high serum cholesterol." (PMID 29370121, 2018).
esophageal squamous cell carcinoma (2 papers, 2014 to 2024). Esophageal squamous cell carcinoma (ESCC) is a type of esophageal carcinoma (EC) that can affect any part of the esophagus, but is usually located in the upper or middle third. "As predicted by applying the CTD database, AKAP12 showed the highest association with esophageal neoplasm/esophageal squamous cell carcinoma, whereas JAM2 showed the lowest correlation." (PMID 39247591, 2024).
lung squamous cell carcinoma (2 papers, 2022 to 2025). "A-kinase anchor protein 12 (AKAP12) has been reported to be related to lung squamous cell carcinoma (LUSC) progression." (PMID 40226362, 2025). "Clinical prognosis analysis showed that AKAP12 expression predicted worse prognoses of various cancer types encompassing colon adenocarcinoma (COAD), OV, GBM, and lung squamous cell carcinoma (LUSC)." (PMID 36110213, 2022). "Using the BEST database, we further investigated the possible correlation between AKAP12 expression and drug sensitivity of VEGF receptor inhibitors in OV, GBM, CRC, and lung squamous cell carcinoma (LUSC) patients." (PMID 36110213, 2022).
osteosarcoma (2 papers, 2017 to 2018). A usually aggressive malignant bone-forming mesenchymal neoplasm, predominantly affecting adolescents and young adults. "SNPs in gravin (AKAP12) were also identified to be significantly associated with breast cancer risk and osteosarcoma." (PMID 29370121, 2018).
retinoblastoma (2 papers, 2021 to 2022). A malignant tumor that originates in the nuclear layer of the retina. "Importantly, we discovered that AKAP12 expression was greatly associated with metastasis of lung adenocarcinoma as well as differential and angiogenesis of retinoblastoma through investigating the single-cell sequencing data." (PMID 36110213, 2022). "A-kinase anchor protein 12 (AKAP12), a scaffolding protein that associates with intracellular molecules, is markedly reduced in the retinas of patients with retinoblastoma, the most common intraocular childhood malignancy, often presenting with iBRB dysfunction." (PMID 34769308, 2021). "In particular, the significantly different results with a correlation coefficient greater than five exhibited a positive association between AKAP12 expression and metastasis in LUAD, as well as angiogenesis and differential in retinoblastoma (RB)." (PMID 36110213, 2022).
thyroid cancer (2 papers, 2022). "First, we verified the expression of 9 immune-related prognostic factors, AKAP12, APOC1, TIMP3, ADAMTS9, ANK2, HTRA3, SYNDIG1, ​​ADAMTS5 and DACT1, in 11 thyroid cancer cell lines in the CCLE database." (PMID 36591507, 2022).
acute leukemia (1 paper, 2022). A clonal (malignant) hematopoietic disorder with an acute onset, affecting the bone marrow and the peripheral blood. "Of note, the AKAP12 expression was found to be diminished in acute leukemia samples, which was associated with an inferior OS." (PMID 36110213, 2022).
adenoma (1 paper, 2020). A neoplasm arising from the epithelium. "On the other hand, among genes overexpressed in adenomas from female patients, AKAP12 (gravin) is a known tumour suppressor and SLC9A9 is associated with epidermal growth factor (EGF) receptor turnover, EGF itself notably involved in corticotrope tumourigenesis." (PMID 32183012, 2020).
adrenocortical carcinoma (1 paper, 2022). "DFS analysis data showed that the reinforced expression of AKAP12 was related to the detrimental prognosis of adrenocortical carcinoma (ACC) (p = 0.0024), cervical squamous cell carcinoma and endocervical adenocarcinoma (CESC) (p = 0.006), COAD (p = 0.0066), LUSC (p = 0.032), STAD (p = 2e-04)." (PMID 36110213, 2022).
age-related macular degeneration (1 paper, 2025). Age-related loss of vision in the central portion of the retina (macula), secondary to retinal degeneration. "We analysed the expression of MT1G, AKAP12 and MAFF in postmortem human retinas with documented age-related macular degeneration (AMD) with geographic atrophy and diabetic retinopathy (DR)." (PMID 40499265, 2025).
aortic stenosis (1 paper, 2018). Aortic valve stenosis is a aortic valve disease caused by the incomplete opening of the aortic valve. "In myocardial biopsies from patients with aortic stenosis (AS, n = 26), AKAP-12, mitochondrial-DNA and PGC-1α expressions were decreased as compared to Controls (n = 13)." (PMID 29717226, 2018).
atherosclerosis (1 paper, 2011). A disease characterized by the build-up of fatty material and calcium deposition in the arterial wall resulting in partial or complete occlusion of the arterial lumen. "Such low AKAP12 expression correlates with reductions in CNN1, a SMC differentiation marker known to be reduced in atherosclerosis." (PMID 21483686, 2011).
cardiac hypertrophy (1 paper, 2025). "AC5 was also proximal to the PKA scaffolding protein AKAP12, along with the discs large MAGUK-scaffold protein 1 (DLG1) which may help to assemble stress-responsive nanodomains for cardiac hypertrophy." (PMID 40749829, 2025).
cardiomyopathy (1 paper, 2017). A disease of the heart muscle or myocardium proper. "In case 7 a 331Kb duplication was identified overlapping AKAP12, a gene that we have previously linked to EA and cardiomyopathy after identifying a deletion intersecting AKAP12 in one EA case." (PMID 29216221, 2017). "In mice homozygous for an Akap12 mutation, there was increased phosphorylation of Cardiac myosin-binding protein C (cMyBPC) which is a known factor in cardiomyopathy in humans." (PMID 29216221, 2017).
cervical cancer (1 paper, 2020). A primary or metastatic malignant neoplasm involving the cervix. "Previous study has shown that AKAP12 expression is enhanced after trans-uterine arterial chemoembolization (TUACE) in cervical cancer patients." (PMID 32849815, 2020).
ciliopathies (1 paper, 2024). "Collectively, it is proposed that the miR‐669a‐5p/G3BP/HDAC6/AKAP12 axis is a promising pharmaceutical target for treating ciliopathies." (PMID 38088586, 2024). "Collectively, these results elucidate a previously unidentified miR‐669a‐5p/G3BP/HDAC6/AKAP12 signaling pathway that regulates cilium length, providing potential pharmaceutical targets for treating ciliopathies." (PMID 38088586, 2024).
cognitive decline (1 paper, 2024). "This phenomenon may support the idea that AKAP12 contributes to cognitive function, as aging is a major risk factor for cognitive decline." (PMID 39574214, 2024).
colitis (1 paper, 2017). Inflammation of the colon. "In the present study, we demonstrated the effect of AKAP12+ colon mesenchymal cells on macrophage phenotypes during dextran sodium sulfate (DSS)-induced colitis." (PMID 28205544, 2017). "We also showed that AKAP12 KO mice were more sensitive to DSS-induced colitis than WT mice, as tissue contraction leads to the generation of M2 macrophages and reduction of the inflammation response during recovery." (PMID 28205544, 2017). "Colon length, which indicates the degree of colon damage, was also shorter in colitis-induced AKAP12 KO mice than in WT mice, whereas it was similar in both genotypes under normal conditions." (PMID 28205544, 2017). "Gene clusters highly correlated with AKAP12 expression in colitis were also involved in focal adhesion and ECM-receptor interaction." (PMID 28205544, 2017). "However, in DSS-induced colitis, it is technically difficult to identify the AKAP12 expression in colon mesenchymal cells since the proportion of mesenchymal cells is changing during inflammation and recovery." (PMID 28205544, 2017). "Interestingly, the difference in the body weight changes between WT and AKAP12 KO mice gradually increased in the later phase of colitis, during which tissue healing and contraction typically occur in a large portion of the inflamed colon." (PMID 28205544, 2017). "Although mechanical differences were observed between the DSS-induced colitis of WT and AKAP12 KO mice, in vivo conditions trigger many other differences between induced colitis in WT and AKAP12KO, which may influence macrophage polarization." (PMID 28205544, 2017). "We next compared the clinical symptoms of colitis in WT and AKAP12 KO mice to determine whether differences in the mechanical environment were correlated with the severity of intestinal inflammation." (PMID 28205544, 2017). "In addition, repetitive DSS-induced colitis experiments confirmed that AKAP12 KO mice were more sensitive to colitis in most experiments." (PMID 28205544, 2017). "Due to these difficulties, we thought that identifying the change of AKAP12 expression in colon mesenchymal cells during DSS-induced colitis is not a simple process and need to be troubleshot." (PMID 28205544, 2017).
colorectal tumor (1 paper, 2022). "For instance, KAP12 expression is downregulated in colorectal tumor tissues, and AKAP12 methylation level was positively associated with tumor grade." (PMID 36148016, 2022).
COVID-19 (1 paper, 2025). A disease caused by infection with severe acute respiratory syndrome coronavirus 2. "Endothelial cell population proportions are significantly altered in COVID-19 livers, with the emergence of a large population of FGFR1 and AKAP12-positive cells that may contribute to angiogenesis and promote fibrosis." (PMID 40087773, 2025).
depression (1 paper, 2021). "For instance, the oncogene S100A9 was upregulated while the tumor suppressor genes HDC, AKAP12, SFRP5, and ALOX15 were downregulated in depression groups." (PMID 34650925, 2021).
diabetic retinopathy (1 paper, 2025). "Notably, in diseased human maculas (AMD and diabetic retinopathy samples) we observed elevated MT1G, AKAP12, and MAFF in Müller glia at the margins, suggesting that macular Müller cells can activate these pathways, but perhaps only in the face of significant stress or damage." (PMID 40499265, 2025).
glioma (1 paper, 2022). A benign or malignant brain and spinal cord tumor that arises from glial cells (astrocytes, oligodendrocytes, ependymal cells). "In this study, we screen three expression arrays associated with the BV resistance of glioma, OV, and NSCLC from the GEO database and identified two DEGs including INSIG1 and AKAP12, both upregulated in the BV-resistant cancer group." (PMID 36110213, 2022).
glomerulonephritis (1 paper, 2012). A renal disorder characterized by damage in the glomeruli. "Thus, AKAP12 plays a critical role in architectural maintenance of glomerular parietal epithelial cells, and AKAP12 deficiency increases the susceptibility to injury-induced glomerulonephritis." (PMID 22811901, 2012).
ischemia (1 paper, 2021). A hypoperfusion of the BLOOD through an organ or tissue caused by a PATHOLOGIC CONSTRICTION or obstruction of its BLOOD VESSELS, or an absence of BLOOD CIRCULATION. "A-kinase anchor protein 12 (AKAP12) alleviated the damage and dysfunction of the BBB after ischemia through the suppression of ROCK." (PMID 34769004, 2021).
ischemic stroke (1 paper, 2020). A stroke disorder caused by obstruction of blood flow to the brain, due to thrombotic (local blood clot formation) or embolic (due to a blood clot or other material traveling from another site) event. "Notably, the leakage of IgG caused by ischemic stroke was exacerbated in Akap12 knockout mice, suggesting the supportive role of endogenous AKAP12 in BBB tightness against ischemic stress." (PMID 33260683, 2020). "Third, the precise mechanism by which ischemic stroke increases the expression level of endothelial AKAP12 still remains to be elucidated." (PMID 33260683, 2020).
lipodystrophy (1 paper, 2009). A congenital or acquired disorder characterized by abnormal loss or redistribution of the adipose tissue in the body. "Others include suppression of Lpin3, a candidate gene for human lipodystrophy; Kpna2, an importin; and AKAP12, a tumor suppressor." (PMID 18925475, 2009).